AADACL2 (arylacetamide deacetylase like 2)
Synonyms: MGC72001
Tractability: Antibody: UniProt places it where antibodies can reach, with medium confidence; UniProt predicts a signal peptide or a membrane-spanning region; its Gene Ontology location is reachable by antibodies, with medium confidence.
Gene: Protein-coding gene on chromosome 3 (151,733,916 to 151,761,339, forward strand). Ensembl gene ENSG00000197953.
Subcellular location: Secreted
Gene Ontology:
Molecular function: carboxylic ester hydrolase activity; catalytic activity; hydrolase activity
Cellular component: membrane; extracellular region
Genetic constraint (gnomAD): Loss-of-function variants: 20 observed, 18.97 expected, observed/expected ratio (o/e) 1.05, 90% interval 0.74 to 1.53. The upper end of that interval is the gene's LOEUF score, 1.53, which puts it in group 6 of 6, group 1 being the genes least tolerant of losing a copy. Missense variants: 426 observed, 453.22 expected, observed/expected ratio (o/e) 0.94, 90% interval 0.87 to 1.02. Synonymous variants: 157 observed, 158.21 expected, observed/expected ratio (o/e) 0.99, 90% interval 0.87 to 1.13.
Homologues: Orthologues: chimpanzee AADACL2 (99% identical), macaque AADACL2 (98% identical), guinea pig AADACL2 (82% identical), mouse Aadacl2 (79% identical), rat Aadacl2 (78% identical), dog AADACL2 (74% identical), Caenorhabditis elegans T09B9.1 (24% identical), Caenorhabditis elegans trcs-1 (24% identical), Caenorhabditis elegans F16F9.4 (23% identical), zebrafish si:dkey-193c22.1 (10% identical). Paralogues in human: AADAC (51% identical), NCEH1 (39% identical), AADACL3 (30% identical), AADACL4 (30% identical), AFMID (13% identical).
Diseases named in the same sentence as AADACL2 in open-access papers:
AADACL2 is named in the same sentence as 6 diseases in open-access papers, as found by Europe PMC text mining. Sharing a sentence is not in itself a finding about the gene and the disease. The quoted sentences say what the papers report.
colorectal cancer (1 paper, 2024). A primary or metastatic malignant neoplasm that affects the colon or rectum. "A model for the early-stage screening of colorectal cancer was created using seven consensus biomarkers (namely ESM1, DHRS7C, OTOP3, AADACL2, LPHN3, GABRD, and LPAR1), and yielded >98% balanced accuracy on external validation." (PMID 39484215, 2024). "AADACL2 is not a known cancer driver, but there is evidence for its role in a comorbid breast-colorectal cancer phenotype." (PMID 39484215, 2024).
ischemic stroke (1 paper, 2024). A stroke disorder caused by obstruction of blood flow to the brain, due to thrombotic (local blood clot formation) or embolic (due to a blood clot or other material traveling from another site) event. "The significant histone modification and regulatory activity of the novel loci near the AADACL2 gene plausibly explain the protection against ischemic stroke demonstrated in this study." (PMID 38317187, 2024).
cancer (2 papers, 2020 to 2024). A tumor composed of atypical neoplastic, often pleomorphic cells that invade other tissues. "A feature space of just seven biomarkers, namely ESM1, DHRS7C, OTOP3, AADACL2, LPHN3, GABRD, and LPAR1, was sufficient to optimize a RandomForest model that achieved > 98% balanced accuracy (and performant recall) of cancer vs. normal on external validation." (PMID 39484215, 2024). "A summary of the models used for building a classifier capable of discriminating between cancer and normal samples based on the expression of seven features: ESM1, DHRS7C, OTOP3, AADACL2, LPHN3, GABRD, and LPAR1." (PMID 39484215, 2024).
AADACL2 also shares sentences with these, for which no sentence is quoted: diabetes (1 paper); dyslipidemia (1); Hypertension (1).